CARD14 (caspase recruitment domain family member 14)
Description:
Acts as a scaffolding protein that can activate the inflammatory transcription factor NF-kappa-B and p38/JNK MAP kinase signaling pathways. Forms a signaling complex with BCL10 and MALT1, and activates MALT1 proteolytic activity and inflammatory gene expression. MALT1 is indispensable for CARD14-induced activation of NF-kappa-B and p38/JNK MAP kinases. May play a role in signaling mediated by TRAF2, TRAF3 and TRAF6 and protects cells against apoptosis. [Isoform 3]: Not able to activate the inflammatory transcription factor NF-kappa-B and may function as a dominant negative regulator.
Synonyms: CARMA2; BIMP2; PRP; PSORS2; PSS1
Tractability: PROTAC: ubiquitination databases record sites on it.
Gene: Protein-coding gene on chromosome 17 (80,169,992 to 80,216,073, forward strand). Ensembl gene ENSG00000141527.
Subcellular location: Cytoplasm (Isoform 1); Cytoplasm (Isoform 2); Cytoplasm (Isoform 3)
Subcellular location (Human Protein Atlas): Cytosol
Gene Ontology:
Molecular function: CARD domain binding; signaling adaptor activity
Biological process: negative regulation of apoptotic process; positive regulation of protein phosphorylation; tumor necrosis factor-mediated signaling pathway; activation of NF-kappaB-inducing kinase activity; positive regulation of canonical NF-kappaB signal transduction; regulation of canonical NF-kappaB signal transduction; regulation of immune response; signal transduction; regulation of apoptotic process
Cellular component: CBM complex; cytoplasm; cytosol; plasma membrane
Genetic constraint (gnomAD): Loss-of-function variants: 107 observed, 102.78 expected, observed/expected ratio (o/e) 1.04, 90% interval 0.89 to 1.22. The upper end of that interval is the gene's LOEUF score, 1.22, which puts it in group 5 of 6, group 1 being the genes least tolerant of losing a copy. Missense variants: 1,313 observed, 1,288.1 expected, observed/expected ratio (o/e) 1.02, 90% interval 0.97 to 1.07. Synonymous variants: 615 observed, 546.57 expected, observed/expected ratio (o/e) 1.13, 90% interval 1.05 to 1.2.
Homologues: Orthologues: chimpanzee CARD14 (99% identical), macaque CARD14 (95% identical), pig CARD14 (78% identical), dog CARD14 (78% identical), guinea pig CARD14 (77% identical), mouse Card14 (77% identical), rat Card14 (76% identical), tropical clawed frog card14 (42% identical), zebrafish card14 (34% identical). Paralogues in human: CARD11 (32% identical), CARD10 (27% identical), CARD9 (15% identical).
Diseases named in the same sentence as CARD14 in open-access papers:
CARD14 is named in the same sentence as 64 diseases in open-access papers, as found by Europe PMC text mining. Sharing a sentence is not in itself a finding about the gene and the disease. The quoted sentences say what the papers report.
psoriasis (86 papers, 2011 to 2025). An autoimmune condition characterized by red, well-delineated plaques with silvery scales that are usually on the extensor surfaces and scalp. "CARD14 is an intracellular NF-κB signaling mediator in the skin, and rare CARD14 variants have been associated with psoriasis and atopic dermatitis." (PMID 41131424, 2025). "We demonstrate here that transgenic mice expressing the psoriasis-associated gain-of-function human CARD14(E138A) mutant specifically in IEC show mild intestinal inflammation, without epithelial damage." (PMID 41131424, 2025). "Among them, CARD14 encodes a keratinocyte protein involved in NF-κB signaling, and variants within this gene have been associated with psoriasis susceptibility, particularly in patients with early-onset and familial disease." (PMID 41010661, 2025). "Another gene, CARD14, is particularly linked to familial cases of psoriasis and severe subtypes of psoriasis, including generalized pustular psoriasis." (PMID 40109802, 2025). "Emerging data confirm that the CARD14 variant rs34367357 is associated with psoriasis in a Pakistani cohort, highlighting its potential role as a susceptibility allele." (PMID 41010661, 2025). "Expression of a psoriasis-associated gain-of-function human CARD14(E138A) mutant protein in intestinal epithelial cells reveals a previously unexplored role for CARD14 in intestinal biology." (PMID 41131424, 2025). "To better understand the effect of CARD14 signaling in the intestine, we generated transgenic mice that express the psoriasis-associated gain-of-function human CARD14(E138A) mutant protein specifically in intestinal epithelial cells." (PMID 41131424, 2025). "Several gain-of-function CARD14 mutations have been found to be associated with psoriasis in humans and murine models, while loss-of-function mutation has been associated with atopic dermatitis." (PMID 41131424, 2025). "Genetic factors such as HLA‐Cw6 and CARD14 mutations, along with environmental factors, contribute to the complex development of psoriasis." (PMID 40539722, 2025). "Mutations in CARD14 have also been identified as causative factors in familial pityriasis rubra pilaris, a rare papulosquamous disorder phenotypically related to psoriasis." (PMID 39145956, 2024). "To investigate further how CARD14 mutations induce psoriasis, we and others have generated knock-in mice that constitutively express psoriasis-associated CARD14 mutations that alter or delete the E138 residue." (PMID 39145956, 2024). "Although it is known that psoriasis-associated CARD14 mutations induce the association of CARD14 with BCL10 and MALT1, knowledge about the signalling proteins and pathways involved in CARD14 signalling is rather limited." (PMID 39145956, 2024). "CARD14 is highly expressed in the skin and mutant forms are independently associated with psoriasis and PRP." (PMID 39104646, 2024). "The activation of NF-κB by gain-of-function psoriasis-associated CARD14 mutants involves CARD14 forming a complex with BCL10 and MALT1." (PMID 39145956, 2024). "CARD14 mutations in psoriasis induce inflammatory cytokines through the MALT1-mediated aberrant activation of NF-κB and JNK signaling pathways." (PMID 38892253, 2024). "Clinical tests identified PSORS2 on chromosome 17q and described CARD14 (caspase recruitment domain-containing protein 14) as being associated with psoriasis." (PMID 38793117, 2024). "PSORS2 contains the CARD14 (caspase recruitment domain family member 14) gene, which encodes for a nuclear factor kB (NF-kB) activator; some of its variations have been linked to common and rare variants of psoriasis." (PMID 38256115, 2024). "It was not possible to obtain primary keratinocytes from patients with psoriasis-associated CARD14 mutations to explore this question due their rarity." (PMID 39145956, 2024).
psoriasis (continued). "It is possible that the genetic association with genes encoding A20 and ABIN1 with psoriasis is due, at least in part, to their direct inhibitory effects on CARD14 signalling." (PMID 39145956, 2024). "Caspase recruitment domain family member 14 (CARD14) is a gene located in the psoriasis susceptibility locus 2 (PSORS2)." (PMID 37372477, 2023). "In this region, the gene CARD14, which encodes the nuclear factor kappa B activator, has been pointed out as a susceptible gene for common forms of psoriasis." (PMID 36837912, 2023). "Studies indicate an association between CARD14 gene expression dysregulation and polymorphism with psoriasis." (PMID 36012602, 2022). "Previously, the association of CARD14 variants with psoriasis was reported in Japanese, Spanish, European, Chinese, and Tunisian populations." (PMID 36012602, 2022). "Spontaneous psoriasis-like phenotype was developed in both models, indicating the CARD14 gain-of-function mutation is sufficient to drive the initiation of psoriasis." (PMID 35075118, 2022). "Studies have suggested an association between autosomal dominant CARD14 (caspase recruitment domain-containing protein 14) gain-of-function mutations with the pathophysiology of psoriasis." (PMID 36012602, 2022). "In this study, for the first time, we reported the association of two nsSNPs, rs2066965 and rs34367357, in the CARD14 gene with psoriasis in Pakistani population." (PMID 36012602, 2022). "Of the IEIs discussed here, GoF variants in CARD14 account for segregation of psoriasis with the Psors2 (17q25-ter) locus on genome-wide linkage scans." (PMID 36733767, 2022). "Several genetic mutations of CARD14 (which maps to the psoriasis susceptibility locus 2 (PSORS2)) have been identified associated with psoriasis susceptibility." (PMID 35075118, 2022). "The involvement of CARD14 in a variety of inflammatory skin disorders reported as the gain-of-function mutations is associated with psoriasis in humans and C57BL/6 mice." (PMID 36190414, 2022). "The relevance of this signaling cascade is highlighted by the association of missense mutations in TLR2 (rs5743708) and CARD14 genes with psoriasis." (PMID 33869291, 2021). "CARD14, which is mainly associated with psoriasis (ongoing clinical studies suggest increased risk of CVDs in psoriasis) and auto-inflammatory disorders, acts as a pro-inflammatory gene by affecting NF-kB activation in the IL-17 inflammation pathway." (PMID 33632238, 2021). "It has been proposed that loss-of-function mutations in CARD14 are associated with severe AD, in contrast to the gain-of-function CARD14 mutations that promote psoriasis." (PMID 32597759, 2020). "Recent studies have investigated how psoriasis-associated CARD14 mutations induce skin inflammation by generating knock-in mice expressing the mouse equivalent CARD14 variants." (PMID 32597759, 2020). "CARD14 variants are also associated with pityriasis rubra pilaris, a rare papulosquamous disorder phenotypically related to psoriasis." (PMID 32597759, 2020). "Autosomal dominant gain of function (GoF) mutations in CARD14 is associated with various entities in the psoriasis disease spectrum." (PMID 32725812, 2020). "CARD14 has been classified as a psoriasis susceptibility gene and many recent studies have focused on demonstrating the role of CARD14 in the pathogenesis of psoriasis." (PMID 31902555, 2020). "The study also showed that psoriasiform inflammatory skin changes were decreased in CARD14-deficient mice, suggesting the possible immune inflammatory role of CARD14 in psoriasis pathogenesis." (PMID 31902555, 2020). "Overexpression of psoriasis-associated mutants of CARD14 in keratinocytes results in enhanced NF-κβ activation and upregulation of psoriasis-associated chemokines (e.g., CCL20 and IL-8)." (PMID 32252279, 2020). "This severe phenotype resembled acute exacerbations of generalised pustular psoriasis (GPP), a rare form of psoriasis that can be caused by CARD14 mutations in patients." (PMID 32597759, 2020).
psoriasis (continued). "CARD14 is known to be selectively expressed in the epidermis, and its gain-of-function mutations are found in the familial type of psoriasis." (PMID 31156649, 2019). "Few studies have sought to better understand the underlying mechanisms linking mutations in CARD14 gene to psoriasis development." (PMID 31130981, 2019). "We describe a family carrying a novel heterozygous mutation in CARD14 gene, with childhood-onset erythrodermic psoriasis requiring an unusual extremely high dose (up to 2 mg/kg every 8 weeks) of ustekinumab to achieve disease remission." (PMID 31286971, 2019). "Previous studies have identified mutations in a gene known as caspase recruitment domain family member 14 (CARD14) gene as a mediator in the immunopathogenesis of psoriasis." (PMID 31130981, 2019). "IL-36γ signals through NF-κB, and various variants—including TNFAIP3 (A20) and CARD14—are thought to exist within psoriasis cells that lead to increased activity of NF-κB." (PMID 29535706, 2018). "CARD14 variants were also found to be associated with another inflammatory skin disorder related to psoriasis, called pityriasis rubra pilaris (PRP)." (PMID 30386326, 2018). "In support of this model, a recent study showed that a single point mutation in CARD14 E138A, which renders CARD14 hyperactive, was sufficient to drive spontaneous psoriasis disease in mice." (PMID 30214442, 2018). "As with psoriasis, most CARD14 variants associated with PRP are heterozygous, with very few compound heterozygous patients having being described." (PMID 30386326, 2018). "It will be of interest to determine the contribution of these cell types, harboring CARD14 mutations, to human psoriasis pathogenesis." (PMID 30386326, 2018). "The rs117918077 (encoding for p.Arg682Trp) polymorphism of the CARD14 gene has been associated with the development of psoriasis and it has also been previously identified in sporadic PRP patient." (PMID 30018619, 2018). "Since these inaugural discoveries, further studies have revealed CARD14 variants associated with various entities in the psoriasis disease spectrum." (PMID 30386326, 2018). "Existence of cofactors have been reported in some studies, therefore it is possible that some CARD14 mutations only confer an increased risk of developing disease and other mutations are needed to develop psoriasis." (PMID 30386326, 2018). "Intriguingly, the expression of CARD14 in aortic endothelial cells was also determined and warrants further investigation into the association of CARD14 mutation and associated cardiovascular defects in some psoriasis patients." (PMID 30386326, 2018). "By screening seven psoriasis cohorts with varying ancestries (over 6,000 cases and 4,000 controls), Jordan and colleagues also identified 15 additional rare and common CARD14 variants that were enriched in cases over controls." (PMID 30386326, 2018). "Subsequently, plenty of sequence variations and mutations in the CARD14 gene have been mapped and associated to psoriasis, pityriasis and other skin disorders phenotipically related to them." (PMID 30319628, 2018). "As CARD14 mutations are only found in a small number of psoriasis kindreds, additional genes responsible for monogenic forms of the disease remain to be identified." (PMID 29186830, 2017). "For example, monogenic forms of psoriasis caused by mutations in CARD14 were revealed through exome sequencing of a family with early-onset psoriasis." (PMID 28193154, 2017). "The most common AID with pustular skin lesions are early onset inflammatory bowel diseases, Majeed syndrome, PAPA syndrome (pyogenic arthritis, pyoderma gangrenosum and acne), IL-36 antagonist deficiency, CARD14-mediated psoriasis, and DIRA." (PMID 26100510, 2015). "Gene Set Enrichment Analysis (GSEA;) showed that published upregulated and downregulated psoriasis transcriptomes were significantly enriched in the transcriptomes of these two patients with CARD14 mutations (Connectivity Scores of 0.69–0.78)." (PMID 25369198, 2014).
psoriasis (continued). "Recent studies indicate that mutations/polymorphisms within CARD14 gene, located within this locus, predispose to psoriasis." (PMID 24005976, 2014). "In conclusion, these findings suggest that individuals with CARD14 mutations exhibit a typical psoriasis phenotype, as substantiated by transcriptome profiling, immunostaining, and expression of CARD14+ and pNF-κB+ ECs." (PMID 25369198, 2014). "In order to further evaluate the relationship between the patients with the CARD14 mutations and classic psoriasis, their transcriptomes were compared." (PMID 25369198, 2014). "Culture of dermal ECs with psoriatic cytokines (such as IFNγ, IL-17, and TNFα) also induced expression of many of the same chemokines found upregulated after transfection of ECs with psoriasis-associated CARD14 mutations." (PMID 25369198, 2014). "It seems that, at least so far, CARD 14 remains the only psoriasis susceptibility gene located within PSORS2 locus." (PMID 24005976, 2014). "CARD14 is a scaffolding protein that regulates NF-κB activation, and psoriasis-associated CARD14 mutations lead to enhanced NF-κB signaling." (PMID 25369198, 2014). "Several of the chemokines that were determined to be upregulated by psoriasis-associated CARD14 mutations in ECs, have been found by previous gene array studies that LS skin contains significantly higher expression of IL-8, CXCL1, and CXCL10 than does NL skin." (PMID 25369198, 2014). "Previous studies had described CARD14 expression in keratinocytes, and transfection of psoriasis-associated CARD14 mutations in KCs resulted in upregulated NF-κB signaling, and increased expression of IL-8 and CCL20." (PMID 25369198, 2014). "Transfection of ECs with psoriasis-associated CARD14 mutations resulted in increased expression of several chemokines, including IL-8, CCL2, and CXCL10." (PMID 25369198, 2014). "The endogenous elicitors of NF-κB signaling specifically through CARD14 however, remains to be determined, and is a critical next step in understanding how CARD14 mutations contribute to psoriasis." (PMID 25369198, 2014). "Mutations in the caspase recruitment domain, family member 14 (CARD14) gene have recently been described in psoriasis patients, and explain the psoriasis susceptibility locus 2 (PSORS2)." (PMID 25369198, 2014). "Transfection of psoriasis-associated CARD14 mutations into HDBECs resulted in increased protein and mRNA of several chemokines, as well as a mild increase in cell adhesions." (PMID 25369198, 2014). "Transfection of dermal ECs with psoriasis-associated CARD14 mutations resulted in increased expression of several chemokines, including CXCL10, IL-8, and CCL2." (PMID 25369198, 2014). "In conclusion, chemokines that were upregulated by transfection of psoriasis-associated CARD14 mutations were found both endogenously in dermal EC within psoriatic lesional skin, as well as upregulated in dermal ECs exposed to key psoriatic cytokines." (PMID 25369198, 2014). "The aim of the study is to evaluate whether CARD14 mutations and the season of treatment initiation influence the efficacy of biologic therapy in psoriasis." (PMID 41010661, 2025). "Our findings suggest that gain-of-function CARD14 mutations may not only predispose patients to psoriasis but also mild intestinal inflammation, reduced intestinal motility, and increased sensitivity to intestinal infection." (PMID 41131424, 2025). "Therefore, functional studies of CARD14 signaling predominantly rely on the ectopic expression of CARD14 psoriasis-associated mutants in cellular and animal models." (PMID 41131424, 2025). "Importantly, rare human CARD14 variants have been associated with psoriasis and atopic dermatitis in patients." (PMID 41131424, 2025). "Additionally, CARD14 variants also have been found to be associated with forms of psoriasis, including (generalized) pustular psoriasis, suggesting that these conditions share pathophysiological mechanisms with PRP." (PMID 40766060, 2025).